HSF1 (heat shock transcription factor 1)
Diseases named in the same sentence as HSF1 in open-access papers (continued):
Sharing a sentence is not in itself a finding about the gene and the disease.
pancreatic cancer (24 papers, 2014 to 2025). "Here the authors show that loss of BRCA function in pancreatic cancer cells leads to HSF1–dependent accumulation of immune-regulatory clusterin-positive cancer associated fibroblasts." (PMID 36316305, 2022). "Mechanistically, a loss of AMPK activation amplified the HSF1 activity to promote the invasion and metastasis of pancreatic cancer." (PMID 30326922, 2018). "Multivariate Cox regression analysis indicated that high HSF1 expression (relative risk = 0.387; P = 0.028) is an independent predictor of OS in patients with pancreatic cancer." (PMID 28482903, 2017). "Our study provides evidence that HSF1 functions as a novel oncogene in pancreatic tumors and is implicated as a target for the diagnosis and treatment of pancreatic cancer." (PMID 28482903, 2017). "In this study, we investigated the ability of HSF1 to regulate the growth and proliferation of pancreatic cancer cells and the underlying mechanism." (PMID 28482903, 2017). "Our study revealed a novel mechanism by which the loss of AMPK activation amplifies the activity of HSF1 to promote the invasion and metastasis of pancreatic cancer." (PMID 28783244, 2017). "We then constructed HSF1-siRNA to investigate the potential of HSF1 to regulate apoptosis, proliferation and the cell cycle of pancreatic cancer cells and the underlying mechanism both in vitro and in vivo." (PMID 28482903, 2017). "Our findings indicate that targeted inhibition of SIRT1 or HSF1 could serve as a promising strategy to sensitize BAP1-deficient pancreatic cancer subtypes to immunotherapy." (PMID 39350280, 2024). "As we all know, KRAS oncogene mutation was a switch of pancreatic cancer initiation, hence, above findings suggested that HSF1 may be a critical molecular for pancreatic cancer tumorigenesis again." (PMID 33422093, 2021). "Moreover, HSF1 is implicated as an independent predictor of survival and prognosis in patients with pancreatic cancer." (PMID 28482903, 2017). "We confirmed that the expression of HSF1 in pancreatic cancer tissue was significantly higher than that in para-cancerous tissues and was significantly associated with poor clinical prognosis in patients with pancreatic cancer." (PMID 28482903, 2017). "HSF1 is a pro-oncogenic factor that is highly expressed for tumor survival in most cancer types, including pancreatic cancer." (PMID 39519208, 2024). "Cooperating with STAT3, HSF1 is able to maintain the cancerous phenotype of liver cancer cells, and the inhibition of HSF1 in pancreatic cancer decreases their stemness and sensitizes them to gemcitabine." (PMID 36765939, 2023). "A study highlighted that CLU expression in pancreatic cancer is regulated by HSF1, a stress-induced master regulator that is known to play a key role in converting fibroblasts into cancer-associated fibroblasts (CAFs) in pancreatic cancer and other cancers." (PMID 38067270, 2023). "The expression of HSF-1 (heat shock factor-1) in patients with pancreatic cancer was studied, and the relationship between HSF-1, an increase in the number of blood vessels, clinical pathological factors, and prognosis was determined." (PMID 35330327, 2022). "In conclusion, all above findings indicated that HSF1 and HSPs were important for the fate change of pancreatic acinar cells, in other words, the initiation of pancreatic cancer." (PMID 33422093, 2021). "We previous found heat shock factor 1 (HSF1) was critical for PDAC progression and the aim of this study was to clarified the mechanisms on early activation of HSF1 and its role in the pancreatic cancer tumorigenesis." (PMID 33422093, 2021). "In conclusion, all the findings above suggested that EGFR mediated HSF1 activation play a key role in pancreatic cancer initiation in vivo and in vitro." (PMID 33422093, 2021). "In this study, we found that pharmacological inhibition of HSF1 slowed pancreatic cancer initiation and suppressed the pancreatitis-induced formation of pancreatic precancerous lesion." (PMID 33422093, 2021).
pancreatic cancer (continued). "In conclusion, the present study demonstrated that HSF1 plays a crucial role in the initiation of pancreatic cancer and that EGFR and its downstream signaling pathway sustain the pro-tumorigenesis effect of HSF1." (PMID 33422093, 2021). "In conclusion, all the findings indicated that there was a correlation between EGFR and HSF1 in the tumorigenesis of pancreatic cancer." (PMID 33422093, 2021). "Having shown that HSF1 regulates the expression of SMAC and mitochondrial apoptosis-related proteins, we used siRNA silencing technology to confirm the role of SMAC in the mechanism by which HSF1 regulates mitochondrial apoptosis in pancreatic cancer cells." (PMID 28482903, 2017). "We found that the KRIBB11 treatment also decreased the staining of Masson's trichrome and the expression of α‐SMA, suggesting that the AMPK‐mediated HSF1 inhibition played a role in suppressing the desmoplastic reaction of pancreatic cancer." (PMID 28783244, 2017). "The knockdown of AMPK in the pancreatic cancer cell lines elevated the expression of HSF1 and promoted the invasion and migration of cancer cells in an HSF1‐dependent manner." (PMID 28783244, 2017). "Our results highlight the important role of AMPK and HSF1 in the inflammatory microenvironment of pancreatic cancer." (PMID 28783244, 2017). "HSF1 was highly expressed in pancreatic cancer tissues and the level of upregulation was found to be closely related to the degree of pancreatic cancer differentiation and poor prognosis." (PMID 28482903, 2017). "In terms of the molecular mechanism, we showed that high expression of HSF1 promotes pancreatic cancer cell proliferation both in vitro and in vivo, increases the mitochondrial membrane potential, inhibits apoptosis and regulates the cell cycle." (PMID 28482903, 2017). "Here, we showed that HSF1 was abnormally activated in pancreatic cancer; however, AMPK was uniformly inactivated." (PMID 28783244, 2017). "Altogether, these data suggested that HSF1 participates in the invasion and migration of pancreatic cancer and the EMT process." (PMID 28783244, 2017). "In vivo tumor growth was significantly lower in the HSF1 group compared with that in the empty vector group, suggesting that HSF1 promotes pancreatic cancer cell proliferation both in vitro and in vivo." (PMID 28482903, 2017). "Here, we showed that pancreatic cancer expressed a high level of HSF1, which is similar to other cancers." (PMID 28783244, 2017). "Here, we found a correlation between the activation of HSF1 and the desmoplastic reaction in pancreatic cancer." (PMID 28783244, 2017). "After HSF1-silencing, we found that pancreatic cancer cell proliferation decreased both in vitro and in vivo and the apoptotic cell ratio increased, while the mitochondrial membrane potential decreased, and the cells were arrested at the G0/G1 phase." (PMID 28482903, 2017). "Following HSF1 silencing, the proliferation of pancreatic cancer cells in vitro and in vivo decreased, the ratio of apoptotic cells increased, the mitochondrial membrane potential decreased, and the cell cycle progression was arrested in the G0/G1 phase." (PMID 28482903, 2017). "The Matrigel invasion assay results showed that the downregulation of HSF1 by the HSF1‐siRNA significantly inhibited the invasion ability of the pancreatic cancer cells (PCs), and we reconfirmed this result in another pancreatic cancer cell line, BxPC‐3." (PMID 28783244, 2017). "HSF1 is reported to be involved in the regulation of apoptosis in pancreatic cancer cells, although the specific mechanism remains to be elucidated." (PMID 28482903, 2017). "HSF1 was abnormally upregulated as pancreatic cancer progressed from low‐grade PanIN1 to invasive PDAC; however, the expression of AMPK showed the opposite pattern." (PMID 28783244, 2017). "It has been reported that HSF1 is highly expressed in pancreatic cancer tissues and inhibits pancreatic cancer cell apoptosis." (PMID 28482903, 2017).
pancreatic cancer (continued). "We then investigated the role of AMPK and HSF1 in the modulation of the inflammatory microenvironment of pancreatic cancer." (PMID 28783244, 2017). "The number of HSF1-positive cells was significantly higher in the pancreatic cancer tissue specimens compared with that in corresponding the para-cancerous tissue specimens." (PMID 28482903, 2017). "To investigate the role of HSF1 in pancreatic cancer invasion and metastasis, we detected the expression of p‐HSF1 in tissues of invasive PDAC and lymph node metastasis." (PMID 28783244, 2017). "Although our preliminary results showed that HSF1 promoted pancreatic cancer cell proliferation, the impact of HSF1 on pancreatic cell apoptosis and cell cycle progression required further investigation." (PMID 28482903, 2017). "We further analyzed the correlation between HSF1 expression and clinical prognosis of pancreatic cancer patients by generating Kaplan–Meier survival curves." (PMID 28482903, 2017). "Our study shows that HSF1 is highly expressed in pancreatic cancer cells, and that its high expression is positively correlated with the degree of tumor differentiation and poor prognosis in pancreatic cancer patients." (PMID 28482903, 2017). "We first examined HSF1 expression in pancreatic cancer tissues by immunohistochemistry, and then studied its clinical significance." (PMID 28482903, 2017). "In terms of the molecular mechanism, we confirmed that HSF1 regulated SMAC to inhibit mitochondrial apoptosis in pancreatic cancer cells, and to promote the occurrence of pancreatic tumors." (PMID 28482903, 2017). "We found that HSF1 promoted the pancreatic cancer invasion and metastasis; the in vivo study showed that the inhibition of HSF1 significantly reduced the tumor burden, suppressed the invasion, and prolonged the overall survival." (PMID 28783244, 2017). "HSF1 expression levels in pancreatic carcinoma were classified as high expression (n = 37) and low expression (n = 13) according to the method described in the Materials and Methods section." (PMID 28482903, 2017). "Hence, we carried out a series in vivo and in vitro studies, and results showed that the EGFR activation mediated pancreatic cancer initiation was partly HSF1 dependent." (PMID 33422093, 2021). "Taken together, HSF1 plays a vital role in the initiation of pancreatic cancer." (PMID 33422093, 2021). "In conclusion, abnormal HSF1 activation is an early molecular event in pancreatic cancer initiation and may participate its tumorigenesis." (PMID 33422093, 2021). "Our previous researchers found that the abnormal activation of HSF1 promoted the invasion and metastasis of pancreatic cancer, along with the observation that high-level HSF1 correlated with the poor prognosis of many cancers, including pancreatic cancer." (PMID 33422093, 2021). "Besides, the pharmacological inhibition of EGFR suppressed the initiation of pancreatic cancer and the activation of HSF1 in vivo." (PMID 33422093, 2021). "In mRNA level, according to TCGA datasets, pancreatic cancer samples which harbored mutant KRAS have a higher level of HSF1 compared to no mutation samples." (PMID 33422093, 2021). "Indeed, we demonstrated that the EGFR activation that mediated pancreatic cancer tumorigenesis was partly HSF1-dependent in vitro." (PMID 33422093, 2021). "As far as we know, this study is the first report describing the role of HSF1 in the clinical pathology and prognosis of pancreatic cancer and demonstrating that HSF1 functions by regulating the SMAC-mediated mitochondrial pathway to inhibit pancreatic cancer cell apoptosis." (PMID 28482903, 2017). "Therefore, we used Western blot to further verify the expression of mitochondrial apoptotic pathway-related proteins in pancreatic cancer cells before and after silencing HSF1." (PMID 28482903, 2017). "Thus, our results demonstrated that HSF1 inhibits mitochondrial apoptosis in pancreatic cancer cells by downregulating SMAC to promote pancreatic tumorigenesis." (PMID 28482903, 2017).
pancreatic cancer (continued). "In vivo, the pharmacological inhibition of HSF1 significantly reduced the tumor burden, decreased the incidence of invasion, and prolonged the overall survival of transgenic mice harboring the spontaneous pancreatic cancer." (PMID 28783244, 2017). "In the present study, we confirmed that HSF1 is highly expressed in pancreatic cancer tissues compared with normal tissues, and is positively correlated with tumor differentiation and poor prognosis in pancreatic cancer patients." (PMID 28482903, 2017). "Thus, our findings indicate that HSF1 inhibits the mitochondrial apoptosis pathway by regulating the expression of SMAC to promote pancreatic cancer cell proliferation and tumor growth." (PMID 28482903, 2017). "HSF1 also plays a key role in regulating the development of various tumors; however, its role in pancreatic cancer and the specific underlying mechanism are not clear." (PMID 28482903, 2017). "The abnormal activation of HSF1 could be mediated by the loss of AMPK activation, and our results revealed that the mechanism by which AMPK activation suppressed the progression of pancreatic cancer is HSF1 dependent." (PMID 28783244, 2017). "Graph showing SMAC index in pancreatic cancer tissues with low or high expression of HSF1." (PMID 28482903, 2017). "HSF1 also promotes the development of pancreatic cancer drug resistance." (PMID 28482903, 2017). "Furthermore, these findings indicate the potential of HSF1 as a novel target for the diagnosis and treatment of pancreatic cancer." (PMID 28482903, 2017). "Given the previous result that metformin‐mediated AMPK activation suppressed the activity of HSF1, we wondered whether HSF1 is required for the AMPK inactivation‐mediated pancreatic cancer invasion and metastasis." (PMID 28783244, 2017). "Here, we show that HSF1 is abnormally activated in pancreatic cancer." (PMID 28783244, 2017). "Next, we investigated the role of HSF1 in the invasion and migration of pancreatic cancer." (PMID 28783244, 2017). "Thus, our results demonstrate a novel molecular mechanism by which HSF1 promotes pancreatic carcinogenesis and implicate HSF1 as an independent predictor of survival and prognosis in patients with pancreatic cancer." (PMID 28482903, 2017). "This study revealed that HSF1 promotes the invasion and metastasis of pancreatic cancer." (PMID 28783244, 2017). "However, little is known about the precise regulation of HSF1 in pancreatic cancer and its role in pancreatic progression." (PMID 28783244, 2017). "All the findings indicated that HSF1 inhibition may suppress the initiation of pancreatic cancer." (PMID 33422093, 2021). "However, the mechanisms of HSF1 abnormal activation during pancreatic cancer initiation and the role of EGFR in this process remains unclear." (PMID 33422093, 2021). "However, whether EGFR pathway and HSF1 interact in pancreatic cancer and their “boss-subordinate relationship” remains unclear." (PMID 33422093, 2021). "However, does EGFR mediated pancreatic cancer initiation was HSF1 dependent remains unclear." (PMID 33422093, 2021). "Next, we treated acinar cells from KC mice with KRIBB11 and found that HSF1 inhibition suppressed the formation of ductal-like spheres, in other words, KRIBB11 inhibited the pancreatic cancer tumorigenesis in vitro." (PMID 33422093, 2021). "Hence, we hypothesized that the abnormal activation EGFR and its downstream pathways may induce PTSs in pancreatic acinar cells and the accumulation/activation of HSF1 in pancreatic cancer tumorigenesis may be a passive response of the cells against to increasing PTSs." (PMID 33422093, 2021). "Another HSF1 inhibitor, KRIBB-11, was found to reduce the motility and invasion of tumor cells in an orthotopic model of pancreatic cancer, proving the anti-EMT activity of the inhibitor of the heat shock response." (PMID 34199046, 2021). "Heat-shock transcription factor 1 (HSF1) downregulates SMAC expression in pancreatic cancer cells, thus promoting pancreatic cancer." (PMID 32325691, 2020).